HOXC10 (homeobox C10)
Diseases named in the same sentence as HOXC10 in open-access papers (continued):
Sharing a sentence is not in itself a finding about the gene and the disease.
lung carcinoma (5 papers, 2020 to 2024). "Our bioluminescence imaging results showed that loss of HOXC10 significantly decreased bone metastasis in KRAS-mutant lung cancer." (PMID 39191757, 2024). "Immunoblot analysis showed that the protein expression levels of HOXC10 in mouse lung cancer spine metastatic tissue were significantly higher than those in adjacent normal tissue, reinforcing the general role of HOXC10 in response to different KRAS mutant variants." (PMID 39191757, 2024). "Here, we identified homeobox C10 (HOXC10) as a lynchpin in pan-KRAS-mutant lung cancer bone metastasis." (PMID 39191757, 2024). "RNA-seq was conducted in KRAS-mutant lung cancer bone metastasis cells of H441-BM upon HOXC10 knockdown." (PMID 39191757, 2024). "In this study, we found that IL6/STAT3 pathway confers resistance to HOXC10 inhibition in KRAS-mutant lung cancer bone metastasis and that activation of p-STAT3Tyr705 further promotes cell survival after HOXC10 inhibition." (PMID 39191757, 2024). "The bioluminescence imaging and micro-CT results demonstrated that inhibition of HOXC10 significantly reduced bone metastasis of KRAS-mutant lung cancer in vivo." (PMID 39191757, 2024). "One study shows that HOXC10 is one of the most pivotal genes that reflects the degree of malignancy of lung cancer, and downregulation of HOXC10 significantly decreases lung cancer metastasis, which are consistent with our results." (PMID 39191757, 2024). "Results from both experiments are consistent and collectively indicate migratory ability of lung cancer cells exhibited 20.6%–73.7% inhibition after HOXC10 knockdown." (PMID 39191757, 2024). "Herein, we explored the association between HOXC10 expression and KRAS-mutant lung cancer bone metastasis." (PMID 39191757, 2024). "First, we assessed the effects of HOXC10 knockdown on cancer cell growth in KRAS-mutant lung cancer bone metastasis cell lines." (PMID 39191757, 2024). "Although HOXC10 inhibition showed promising benefits in KRAS-mutant lung cancer bone metastasis in vivo, we found that the ability of inhibiting bone metastasis by HOXC10 knockdown was significantly diminished 28 days after intracardiac injection." (PMID 39191757, 2024). "To investigate the link between KRAS-mutant variants and HOXC10 expression, we obtained spine metastatic tissue with KRAS mutations including G12V/S and Q61H that mutation commonly occur in human lung cancer." (PMID 39191757, 2024). "Intriguingly, inhibition of HOXC10 plus STAT3 inhibitor in combination was effective against KRAS-mutant lung cancer bone metastasis by triggering ferroptosis." (PMID 39191757, 2024). "Strikingly, inhibition of HOXC10 in combination with STAT3 inhibitor was effective against KRAS-mutant lung cancer bone metastasis by triggering ferroptosis." (PMID 39191757, 2024). "We measured the apoptotic capacity by Annexin V staining and observed that the apoptosis of KRAS-mutant lung cancer bone metastasis cells increased 5.2-fold to 15.6-fold after HOXC10 knockdown." (PMID 39191757, 2024). "Altogether, this study reveals a previously unrecognized role of HOXC10 in pan-KRAS-mutant lung cancer bone metastasis, and suggests HOXC10 as a therapeutic target for treating this intractable disease." (PMID 39191757, 2024). "We propose a regimen of dual inhibition of HOXC10 and STAT3 for improving the effectiveness of HOXC10 inhibition alone in KRAS-mutant lung cancer bone metastasis." (PMID 39191757, 2024). "As expected, TTI-101 potentiated the inhibition efficacy of HOXC10 knockdown on lung cancer metastatic capacity by bioluminescence imaging analysis." (PMID 39191757, 2024). "Taken together, these findings reveal that HOXC10 effectively alleviates pan-KRAS-mutant lung cancer with bone metastasis in the NOD1/ERK axis-dependent manner, and support further development of an effective combinatorial strategy for this kind of disease." (PMID 39191757, 2024).
lung carcinoma (continued). "As the bone metastasis of lung cancer cells can lead to osteolytic lesions and induction of osteoclastogenesis, we next tested whether HOXC10 drives KRAS-mutant lung cancer cells to trigger osteoclastogenesis." (PMID 39191757, 2024). "We found that HOXC10 may serve as a novel biomarker of KRAS-mutant lung cancer bone metastasis, implying the multifaceted role of HOXC10 in KRAS-mutant lung cancer bone metastasis and broadening the application of HOXC10-based therapy." (PMID 39191757, 2024). "However, the biological function of HOXC10 in KRAS-mutant lung cancer bone metastasis is still unclear." (PMID 39191757, 2024). "Our results showed that the cell growth inhibition rates of the HOXC10 inhibition reached 53.2%–85.3% compared to those of the empty vector group of KRAS-mutant lung cancer bone metastasis cells, according to colony formation, CCK8, LDH release, and EDU assays." (PMID 39191757, 2024). "Notably, a regimen of dual inhibition of HOXC10 and STAT3 is established to improve the effectiveness of HOXC10 inhibition alone in KRAS-mutant lung cancer bone metastasis." (PMID 39191757, 2024). "Moreover, we revealed a new mechanism mediated by DNA demethylation and G4 formation in promoting HOXC10 expression and lung cancer development." (PMID 32687064, 2020). "Our analyses of HOXC10 function in lung cancer further supported this notion." (PMID 32687064, 2020). "However, little is known about HOXC10’s expression and function in lung cancer." (PMID 32687064, 2020). "To further explore the clinical benefit of HOXC10 inhibition in patients, we constructed a mini patient-derived xenograft (mini-PDX) model with KRASG12C mutant lung cancer bone metastasis." (PMID 39191757, 2024). "Collectively, these findings demonstrate that HOXC10 depletion can suppress proliferation and migration and promote apoptotic ability in KRAS-mutant lung cancer bone metastasis cells." (PMID 39191757, 2024). "Taken together, our work indicates that HOXC10/NOD1/ERK signaling can be a promising target for preventing and treating lung cancer bone metastasis." (PMID 39191757, 2024). "Our experiments showed that HOXC10 inhibition impeded the proliferation and migration of KRAS-mutant lung cancer cells in vitro and attenuated osteolytic bone metastasis in vivo." (PMID 39191757, 2024). "Altogether, these results demonstrate that HOXC10 inhibition and TTI-101 combination has dramatic effects on key ferroptosis mediators in KRAS-mutant lung cancer bone metastasis cells, including cellular ROS and GSH levels." (PMID 39191757, 2024). "However, the expression and functions of HOXC10 in lung cancer remains unknown." (PMID 32687064, 2020). "We also explored the clinical significance of HOXC10 expression in different KRAS-mutant lung cancer patients with/without bone metastasis." (PMID 39191757, 2024). "We next evaluated whether activated HOXC10 coordinated with oncogenic KRAS and played a promoting role in bone metastasis of lung cancer development." (PMID 39191757, 2024). "Preinduced primary preosteoclasts were exposed to conditioned medium from H441 and A549 KRAS-mutant lung cancer cells with or without HOXC10 knockdown." (PMID 39191757, 2024). "KRAS-mutant lung cancer bone metastasis tissue exhibited higher p-STAT3Tyr705 levels at day 28 after intracardiac injection than at day 7, suggesting that activation of IL6/JAK/STAT3 pathway may be involved in the enhanced resistance to HOXC10 inhibition." (PMID 39191757, 2024). "Therefore, our results uncover that HOXC10 upregulation plays an important role in the aggression and metastasis in LUAD, which might be a potential target for treatment of lung cancer and an independent factor for the prognosis of LUAD." (PMID 38154103, 2023).
esophageal squamous cell carcinoma (4 papers, 2021 to 2025). Esophageal squamous cell carcinoma (ESCC) is a type of esophageal carcinoma (EC) that can affect any part of the esophagus, but is usually located in the upper or middle third. "Although recent studies have identified some mutations linked to the development of squamous cell carcinoma of the esophagus (ESCC), the specific role of HomeoboxC10 (HOXC10) in the pathogenesis still requires further investigation." (PMID 37876483, 2023). "They further confirmed that ERBB3 silencing decreased PI3K and AKT phosphorylation upregulated by HOXC10 and significantly reduced esophageal squamous cell carcinoma cells proliferative capacity." (PMID 34113572, 2021). "In terms of functionality, increased expression of miR-4739 has been observed to inhibit the growth of esophageal squamous cell carcinoma (ESCC) cells by suppressing the expression of homeobox C10." (PMID 38267862, 2024). "Therefore, our study further confirms that HOXC10 plays a crucial role in tumor progression in ESCC and provides a new avenue to understand tumor malignancy in esophageal squamous cell carcinoma." (PMID 37876483, 2023).
glioblastoma (4 papers, 2020 to 2024). The most malignant astrocytic tumor (WHO grade IV). "used bioinformatics to identify four survival-associated differentially expressed genes (OSMR, HOXC10, SCARA3, and SLC39A10) in glioblastomas and found that glioblastoma patients with abnormal HOXC10 expression had poor survival outcomes." (PMID 34113572, 2021). "For example, HOXC10 is highly expressed in glioblastoma, and HOXC10 upregulation activates PI3K/AKT signaling pathway to promote glioblastoma cell proliferation and accelerate poor prognosis of glioblastoma." (PMID 35201457, 2021). "Hoxc6 and Hoxc10 overexpression regulates glioblastoma cell proliferation and migration via MAPK and PI3K/protein kinase B (AKT) signaling pathways, respectively." (PMID 33402862, 2020). "Moreover, HOXC10 knockdown inhibited the glioblastoma U87 cells proliferation, migration, and invasion." (PMID 34113572, 2021).
hepatocellular carcinoma (4 papers, 2020 to 2023). A malignant tumor that arises from hepatocytes. "However, the association between HOXC10 and hepatocellular carcinoma (HCC) remains to be elucidated." (PMID 37733108, 2023). "HOXC10 overexpression mediated by Interleukin 1β facilitates hepatocellular carcinoma (HCC) metastasis." (PMID 34722321, 2021). "Interestingly, inflammatory factor IL-1β can also promote HOXC10 expression via the JNK/c-Jun pathway and induce invasion and metastasis of hepatocellular carcinoma, indicating that HOXC10 can promote tumor metastasis by cooperating with inflammatory cytokines." (PMID 34113572, 2021).
oral cancer (4 papers, 2022 to 2025). "In oral cancer research, HOX genes such as HOXC10 are continuously upregulated from precancerous lesions to malignant stages, and the HOXC10-encoded protein can bind to the MTFR2 promoter region to promote transcription." (PMID 40748969, 2025). "In contrast, HOXA7, HOXA10, HOXB7, HOXC6, HOXC10, HOXD10, and HOXD11 were consistently upregulated in potentially malignant oral lesions as they advanced to oral cancer." (PMID 41477365, 2025). "HOXA7, HOXA10, HOXB7, HOXC6, HOXC10, HOXD10, HOXD11 showed consistent upregulation in the potentially malignant oral lesions through their progression to oral cancer, which indicated the posterior prevalence of the HOX genes during cancer progression." (PMID 35710803, 2022).
liver cancer (3 papers, 2018 to 2023). An epithelial or non-epithelial malignant neoplasm that arises from the liver. "In particular, HOXC10 was known to be associated with a decrease in the overall survival rate of liver cancer." (PMID 30065750, 2018). "This discrepancy regarding the function of HOXC10 in liver cancer may be associated with the heterogeneity of tumors and different downstream signaling pathways." (PMID 37733108, 2023). "HOXC10 expression is inhibited by miR-221, and inhibition of represses cell proliferation in liver cancer through the activation of MAPK signaling pathway." (PMID 35201457, 2021).
non-small cell lung carcinoma (3 papers, 2020 to 2021). A group of at least three distinct histological types of lung cancer, including non-small cell squamous cell carcinoma, adenocarcinoma, and large cell carcinoma. "Half of the KRAS-mutant NSCLC (non-small-cell lung cancers) express the homeobox protein HOXC10, which triggered tumour regression in xenografts and PDX (patient-derived xenografts) models in vivo." (PMID 33375038, 2020). "In the current study, we examined the expression and function of HOXC10 in human non-small cell lung cancer (NSCLC)." (PMID 32687064, 2020).
Obesity (3 papers, 2013 to 2025). Accumulation of substantial excess body fat. "Here we described for the first time that obesity down-regulates expression of TBX15 and HOXC10 in subcutaneous WAT resident stem cells." (PMID 24040759, 2013).
ovarian carcinoma (3 papers, 2020 to 2023). A malignant neoplasm originating from the surface ovarian epithelium. "HOXC10 was associated with metastasis and poor prognosis in ovarian cancer." (PMID 32897245, 2020). "The function of HOXC10 in ovarian cancer metastasis was investigated in vitroand via intraperitoneal injection in vivo." (PMID 32897245, 2020). "This study provides the first evidence that HOXC10 promotes ovarian cancer metastasis by regulating the transcription of the EMT-related gene Slug." (PMID 32897245, 2020). "A Cox regression analysis was further to evaluate and analyze the potential of HOXC10 as a prognostic biomarker in ovarian cancer." (PMID 32897245, 2020). "Here, HOXC10 expression was examined in ovarian cancer tissues." (PMID 32897245, 2020). "In vitro, HOXC10 overexpression promoted ovarian cancer cell migration." (PMID 32897245, 2020). "Interestingly, a recent study revealed that upregulation of HOXC10 in ovarian cancer could promote ABCC3 expression by transcriptional upregulation of β-catenin, resulting in carboplatin resistance." (PMID 37334354, 2023). "Univariate survival showed that age (P=0.077) and histologic type (P=0.062) were not concerned with ovarian cancer overall survival, and FIGO stage (P=0.011), survival state (P=0.004), distant metastasis (P=0.013) and HOXC10 expression level (P=0.005) were associated with overall survival." (PMID 32897245, 2020).
prostate carcinoma (3 papers, 2015 to 2024). A carcinoma that arises from epithelial cells of the prostate gland. "Among these, two homeobox genes, HOXC10 and HOXD10, and TMSB15A, encoding for thymosin-beta-15A, a tumor motility gene promoting metastases in prostate cancer, all overexpressed in STCs vs LTCs." (PMID 26188123, 2015). "By contrast, GO analysis of the genes upregulated in the BPH-PCa group while downregulated in men with symptomatic BPH were several transcription factors related to prostate cancer, such as NKX3-1 and members of the HOX family like HOXB13, HOXB7, HOXD4, HOXC10 and HOXC8." (PMID 38201640, 2024).
thyroid cancer (3 papers, 2017 to 2023). "HOXC10 encourages the invasion and migration of thyroid cancer cells, suggesting its potential significance as a novel biomarker for predicting the prognosis of human thyroid cancer." (PMID 37876483, 2023). "Hoxc10 triggers metastasis and invasion in thyroid cancer and the expression of Hoxc10 is inversely related to patient survival time." (PMID 33402862, 2020).
melanoma (2 papers, 2021 to 2025). A malignant, usually aggressive tumor composed of atypical, neoplastic melanocytes. "Additionally, HOXC10 deficiency repressed tumor growth and lung metastasis of melanoma through the inhibition of Slug and YAP/TAZ signaling pathway." (PMID 35201457, 2021). "Additionally, HOXC10 deficiency decreased melanoma cell migration, invasion and EMT." (PMID 35201457, 2021). "Thus, up-regulation of HOXC10 may be associated with melanoma development." (PMID 35201457, 2021). "We separated melanoma tissues and the matched tumor-adjacent normal tissues from melanoma patients, and examined HOXC10 expression in the melanoma cells and tissues." (PMID 35201457, 2021). "Our in vitro assays have found that HOXC10 silencing inhibited proliferation and clone formation, and enhanced apoptosis of melanoma cells." (PMID 35201457, 2021). "These deta taken together showed that HOXC10 knockdown inhibited tumor growth and lung metastasis of melanoma in mice." (PMID 35201457, 2021). "The in vitro assays demonstrated that inhibition of HOXC10 significantly repressed tumor growth and lung metastasis of melanoma in mice by inhibiting Slug and YAP/TAZ signaling pathway." (PMID 35201457, 2021). "We initially compared HOXC10 expression between melanoma tissues and tumor-adjacent normal tissues of patients with melanoma." (PMID 35201457, 2021). "In this work, we found that HOXC10 overexpression enhanced Slug expression, while HOXC10 silencing reduced Slug expression in melanoma cells." (PMID 35201457, 2021). "In order to determine the function role of HOXC10 in melanoma, HOXC10 was silenced in A375 and A2058 cells that express relatively higher expression of HOXC10." (PMID 35201457, 2021). "In conclusion, this work demonstrated that HOXC10 promoted growth and migration of melanoma by regulating Slug to activate the YAP/TAZ signaling pathway." (PMID 35201457, 2021). "In vitro melanoma cell lines also exhibited upregulation of HOXC10 mRNA and protein." (PMID 39858044, 2025). "Taken together, these findings indicated that HOXC10 promoted melanoma development." (PMID 35201457, 2021). "In addition, TCGA and CCLE database reveal that HOXC10 is highly expressed in the tumor tissues of melanoma." (PMID 35201457, 2021). "HOXC10 was highly expressed in the melanoma tissues and cells." (PMID 35201457, 2021). "Comparing with the tumor-adjacent normal tissues, HOXC10 was up-regulated in melanoma tissues." (PMID 35201457, 2021). "Finally, our in vivo assays demonstrated that inhibition of HOXC10 significantly repressed tumor growth and lung metastasis of melanoma in the tumor xenografts mice." (PMID 35201457, 2021). "Next, we estimated the impact of HOXC10 on cell apoptosis in melanoma cells." (PMID 35201457, 2021). "Here, we first determined the biological role of HOXC10 in melanoma." (PMID 35201457, 2021). "Moreover, HOXC10 inhibition suppressed cell proliferation, clone formation and promoted apoptosis of melanoma cells." (PMID 35201457, 2021). "Finally, to verified the function role of HOXC10 in melanoma, we constructed tumor xenografts of melanoma in mice." (PMID 35201457, 2021). "Here, we attempted to determine whether HOXC10 can affect the development of melanoma." (PMID 35201457, 2021). "However, the mechanism of action of HOXC10 in the progression of melanoma is still remains unclear, and further research is still needed in melanoma." (PMID 35201457, 2021). "Therefore, this study suggests that inhibition of HOXC10 has therapeutic potential in melanoma." (PMID 35201457, 2021). "Knockdown of HOXC10 also retarded migration, invasion and epithelial–mesenchymal transition (EMT) in melanoma cells." (PMID 35201457, 2021). "However, the involvement of HOXC10 in melanoma is still unknown." (PMID 35201457, 2021). "However, whether HOXC10 has an oncogenic effect in melanoma is currently unclear." (PMID 35201457, 2021).
melanoma (continued). "HOXC10 was upregulated in melanoma patient tissue compared to non-cancerous adjacent tissues from a cohort of 60 patients." (PMID 39858044, 2025). "Therefore, this work attempted to investigate whether HOXC10 can regulate Slug expression to activate the YAP/TAZ signaling pathway, thereby promoting the growth and metastasis of melanoma." (PMID 35201457, 2021).
carcinoma of the lip (1 paper, 2022). "HOXA5, HOXB9, HOXC8, HOXC10, and HOXC11 genes were specific to certain sites of the oral cavity whereas HOXA10 was associated with the development of the carcinoma of the lip and oral cavity." (PMID 35710803, 2022).
colon adenocarcinoma (1 paper, 2023). "HOXC10 was negatively associated with immune score in most cancers except colon adenocarcinoma." (PMID 38154103, 2023).